RN7SKP257 (RN7SK pseudogene 257)
Gene: Miscellaneous RNA gene on chromosome 14 (36,593,839 to 36,594,147, reverse strand). Ensembl gene ENSG00000201395.
Homologues: Orthologues: chimpanzee 7SK (98% identical). Paralogues in human: RN7SKP90 (77% identical), RN7SKP180 (76% identical), RN7SKP203 (75% identical), RN7SKP245 (75% identical), RN7SKP176 (74% identical), RN7SKP255 (74% identical), RN7SKP79 (74% identical), RN7SKP20 (73% identical), RN7SKP273 (73% identical), RN7SKP71 (73% identical), 7SK (73% identical), RN7SKP78 (73% identical), and 284 more.